ALDH1A1 (aldehyde dehydrogenase 1 family member A1)
Diseases named in the same sentence as ALDH1A1 in open-access papers (continued):
Sharing a sentence is not in itself a finding about the gene and the disease.
breast carcinoma (continued). "In breast cancer, SIRT2 can be activated by NOTCH signalling, leading to the deacetylation and activation of high aldehyde dehydrogenase (ALDH1A1), thereby promoting breast cancer progression." (PMID 36101744, 2022). "Based on its enzymatic activity, ALDH1A1 reduces the intracellular pH of breast cancer cells and upregulates GMCSF by activating the TAK1-NFkB signaling pathway." (PMID 36387165, 2022). "To ensure the clinical relevance of BCSC-associated marker and RICH1, we assessed the expression of RICH1 and ALDH1A1 by IHC in 30 breast cancer samples." (PMID 35064101, 2022). "Aldehyde dehydrogenase 1A1 (ALDH1A1) is a cancer stem cell (CSC) marker related to clinical outcomes in breast cancer (BC)." (PMID 36139578, 2022). "determined the RNA expression of ALDH1A1 in breast cancer cells and found that ALDH1A1 overexpression contributed functionally the proliferation, adhesion, migration, extravasation, and micrometastasis of breast cancer." (PMID 35814382, 2022). "The breast cancer stemness marker ALDH1A1 activates ALDH1A1/HIF-1α/VEGF axis through retinoic acid conduction, upstream HIF-1α is activated, induces VEGF expression and release, and promotes tumor angiogenesis." (PMID 36387165, 2022). "The prognostic significance of ALDH1A1 in breast cancer, ALDH1 in rectal cancer, ALDH1 in esophageal cancer, and ALDH2 in oropharyngeal cancer has been explored by scholars." (PMID 34928471, 2022). "Western blot and qRT-PCR analysis showed that Tanshinone IIA decreased Oct3/4 and ALDH1A1 expression in breast cancer cells." (PMID 35057866, 2022). "ALDH1A1 also enhances the USP28/MYC signaling pathway to promote breast cancer stem cells by maintaining a local acid microenvironment." (PMID 36387165, 2022). "ALDH1A1 is highly expressed in breast cancer cells, and the knockdown of ALDH1A1 can significantly sensitize breast cancer cells to chemotherapy and radiotherapy." (PMID 35814382, 2022). "DEAB mainly acts on ALDH1A1 and 3A1 showing the inhibition of tumor growth and metastatic spreading in a mouse model of breast cancer." (PMID 35299840, 2022). "For instance, SIRT2 can promote breast cancer development by deacetylating Slug and aldehyde dehydrogenase 1A1 (ALDH1A1)." (PMID 34368168, 2021). "Numerous studies suggest that the expression of ALDH1A1 suggests a poor prognosis for breast cancer." (PMID 34198652, 2021). "Another study reported that tamoxifen was found to bind directly to and activate ERα-36 through transcriptional stimulation of aldehyde dehydrogenase 1A1 (ALDH1A1) that enhanced the stemness and ability to metastasize of breast cancer cells." (PMID 35096574, 2021). "An ALDH1A1 promoter-driven tdTomato is reported for evaluating the drug sensitivity in breast cancer and colon cancer cell lines." (PMID 34150761, 2021). "In the face of cancer, ALDH1A1 is regarded as a marker of breast cancer stem cells, and cancer stem cells have strong carcinogenicity and self-renewal ability, and play an important role in tumorigenesis, development, and prognosis." (PMID 34198652, 2021).
breast carcinoma (continued). "We found higher ALDH1A1 expression in molecularly aggressive breast cancer consisting of 42.9% of the ALDH1A1 positive group (21 out of 49), suggesting an association of ALDH1A1 with aggressive breast carcinoma." (PMID 34778599, 2021). "In Kaplan-Meier survival analysis, either high CPA4 or ALDH1A1 levels was significantly correlated with poor survival in breast cancer patients." (PMID 33746592, 2021). "Kaplan-Meier survival analysis showed that CPA4 and ALDH1A1 over-expression was significantly correlated with overall survival of breast cancer patients." (PMID 33746592, 2021). "High expression of CD47, CD49c, CD44, and ALDH1A1 suggests the breast cancer origin of the KAIMRC2 cell line." (PMID 34073849, 2021). "Kaplan-Meier survival analysis showed that breast cancer patients with high levels of ALDH1A1 or CPA4 were significantly correlated with poor overall survival." (PMID 33746592, 2021). "ALDH1-A1 is an important marker of CSCs and its high expression is correlated with poorer overall survival in breast cancer patients." (PMID 34548908, 2021). "This is in agreement with Zhang and colleagues who established long-term culture from CTCs ALDH1A1(+); EpCAM(−) in breast cancer suggesting that this CTC population was able to form brain metastasis." (PMID 34071445, 2021). "Cells with high ALDH activity are considered to possess stem cell-like properties in both normal and malignant cells and ALDH1A1 expression has been shown to correlate with higher metastasis and worse prognosis in clinical samples of breast cancer." (PMID 32423137, 2020). "Herein, betulinic acid treatment significantly elevated Cav-1 expression whereas attenuated the stemness-related protein ALDH1A1 in mammary tumors of MMTV-PyVT+/- breast cancer spontaneous mice." (PMID 32528105, 2020). "The results of our previous experiment with clove buds showed a significant decrease in CD24 and CD44 expression, and on the other hand, an increase in ALDH1A1 expression in treated mammary carcinomas." (PMID 32204409, 2020). "We have documented the contribution of ALDH1A1 in tumor angiogenesis in breast cancer cells by the activation of hypoxia inducible factor-1α and vascular endothelial growth factor signaling." (PMID 35582039, 2020). "The silencing of the ALDH1A1 gene in human breast cancer cells increases their sensitivity to paclitaxel with a concomitant increase of ROS formation, and similar results were obtained with doxorubicin, sorafenib, and staurosporine." (PMID 35582039, 2020). "We modulated ALDH1A1 and HTRA2 expression in CCR2 deficient and breast cancer cell lines with induced or endogenous CCR2 overexpression." (PMID 31208996, 2019). "ALDH1br human breast cancer cells with low levels of ALDH1A1 acetylation display self-renewal characteristics." (PMID 30733805, 2019). "To examine how ALDH1A1 functioned in a breast cancer cell line with high levels of endogenous CCR2, we knocked down ALDH1A1 by stable shRNA expression in parental DCIS.com cells." (PMID 31208996, 2019). "For example, liver cancer and kidney cancer show high level of ALDH1A1, whereas breast cancer, ovary cancer, skin cancer, pancreatic cancer, and esophagus cancer express higher level of ALDH1A3." (PMID 30220009, 2019). "Using 3D cell culture and transwell invasion systems, we report that CCL2/CCR2 signaling regulates breast cancer cell growth and invasion in part by enhancing ALDH1A1 expression and suppressing HTRA2 expression." (PMID 31208996, 2019). "Disulfiram was previous performed an effective inhibitor which targeted at ALDH1A1, dramatically downregulated the expression of ALDH1A1 in breast cancer." (PMID 31596733, 2019). "Expression of ALDH1A1 by CSCs has been demonstrated in multiple types of cancers, such as human breast cancer, lung cancer, and colon cancer." (PMID 30733805, 2019).
breast carcinoma (continued). "In summary, CCL2/CCR2 chemokine signaling regulates breast cancer cell growth and invasion through increased ALDH1A1 expression and suppression of HTRA2." (PMID 31208996, 2019). "The combined NRF1 overexpression and treatment with E2 also led to reprogramming of CD24+ and CD24−CD44− subpopulations with multiple breast cancer stem cell signatures containing ALDH1A1, EpCAM, CXCR4, or CD133." (PMID 30486409, 2018). "We examined ALDH1A1 expression and activity in a panel of cell lines representing different breast cancer histotypes, namely MCF-7, MDA-MB-231 and SKBR-3." (PMID 30541574, 2018). "That treatment increases ALDH1A1 positivity has been shown in breast cancer biopsies taken pre- and post-chemotherapy, although this occurred in a minority of samples." (PMID 30308036, 2018). "Reduced mammosphere formation, cell invasion and migration in vitro were observed in ALDH1A1 knockdown breast cancer cells after 4-OHT treatment." (PMID 29393296, 2018). "Another relatively small study observed that a poor response to neoadjuvant chemotherapy is related to an increase in ALDH1A1 levels after therapy in breast cancer patients." (PMID 30308036, 2018). "A transwell system was used to assess the angiogenic features of human umbilical vein endothelial cells (HUVEC) when co-cultured with breast cancer cells MCF-7 harboring different levels of ALDH1A1." (PMID 30541574, 2018). "The evidence gathered in this work shows that ALDH1A1 promotes robust angiogenesis in vitro and in vivo in breast cancer cell lines inoculated in mice, by inducing VEGF expression and release, as a consequence of upstream HIF-1α activation." (PMID 30541574, 2018). "Our findings show that both molecules increase epithelial to mesenchymal transition and migratory capacity of breast cancer cells, as well as cancer stem cell numbers, by increasing the expression of pluripotency genes such as ALDH1A1, KLF4, and NANOG." (PMID 30131941, 2018). "The ALDH1A1 subtype of breast cancer stem cells has been found to be responsible for resistance to chemotherapeutic drugs." (PMID 29433490, 2018). "All together the results demonstrate that ALDH1A1 activity in MCF-7 breast cancer cells orchestrated both the stemness and the angiogenic output." (PMID 30541574, 2018). "Overall, the results of this study support the concept that ALDH1 plays a functional role in both breast cancer metastasis and therapy resistance; although the ALDH1A1 and ALDH1A3 isozymes seemed to contribute to these behaviors in different ways." (PMID 28937653, 2017). "In contrast, our data shows that knockdown of ALDH1A1 consistently reduces most steps in the metastatic cascade except for basic proliferation in two different human breast cancer cell lines with different genetic backgrounds and differing metastatic ability." (PMID 28937653, 2017). "Malignant breast cancer cell behavior in vitro was assessed in response to direct knockdown of ALDH1A1 or ALDH1A3 by siRNA." (PMID 28937653, 2017). "C/EBPβ is a transcriptional regulator of aldehyde dehydrogenase 1A1 (ALDH1A1), a member of a family of detoxifying enzymes responsible for oxidizing aldehydes, in breast cancer cells." (PMID 28148901, 2017). "The ALDH1A1 isozyme has been shown to have increased expression in breast cancer patients who present with positive lymph nodes and in patients who succumb to their disease." (PMID 28937653, 2017). "Further, a recent meta-analysis indicates that ALDH1A1 can be used as an indicator of poor prognosis in breast cancer patients." (PMID 26783961, 2016). "In breast cancer, ALDH1A1 expression is a good CSC marker and an important predictor of progression and poor survival." (PMID 26783961, 2016). "ALDH1A1 and CD133 have been reported as cancer stem cell markers and overexpression of EMT markers on CTCs is often accompanied by ALDH1 expression in breast cancer at all stages of the disease." (PMID 27013581, 2016).
breast carcinoma (continued). "ALDH1A1 is also associated with worse PFS and OS in clear cell renal cell carcinoma and breast cancer patients treated with neo-adjuvant chemotherapy." (PMID 25788273, 2015). "In this study, we analyzed the association between mRNA expression of the ALDH1A1 gene in tumor tissues, and the clinical outcomes in patients with TNBC in three cohorts of breast cancer patients." (PMID 26462023, 2015). "Two other studies on all types of breast cancer combined also reported that the ALDH1A1 protein was a potential predictive marker of early local tumor recurrence and distant metastasis." (PMID 26462023, 2015). "General agreement also exists that ALDH1A1 correlates with ER– status in breast cancers and is an independent predictor of poor clinical outcome." (PMID 24887554, 2014). "Aldehyde dehydrogenase 1 family member A1 (ALDH1A1) has been identified as a putative cancer stem cell (CSC) marker in breast cancer." (PMID 24938375, 2014). "The prognosis of breast cancer patients with ALDH1A1+ tumors was poorer than that of the ALDH1A1- patients." (PMID 24938375, 2014). "Our results derived from the meta-analysis of existing studies indicated that ALDH1A1 can be used as a poor prognostic indicator in breast cancer patients." (PMID 24938375, 2014). "We will further study the influence of ALDH1A1 expression on differentiation, invasion, and metastasis of breast cancer cells." (PMID 24938375, 2014). "Except in the study by Neumeister, immunohistochemistry (IHC) was a primary method used to evaluate ALDH1A1 expression in breast cancer specimens." (PMID 24938375, 2014). "Because of the important role performed by breast CSCs in tumorigenesis, development, and therapeutic outcomes, many groups have investigated the relationship between the expression of ALDH1A1 and the clinicopathologic features of breast cancer patients." (PMID 24938375, 2014). "The high expression of ALDH1A1 is positively associated with larger tumor size, higher histological grade and a greater likelihood of LNM in breast cancer patients." (PMID 24938375, 2014). "Several recent studies on breast cancer stem-cells indicate altered regulation of DNA repair networks, particularly an inverse relationship between ALDH1A1 status and BRCA1 gene expression." (PMID 25216266, 2014). "Our results indicate that ALDH1A1 is a biomarker to predict tumor progression and poor survival of breast cancer patients." (PMID 24938375, 2014). "Sunitinib increases the population of aldehyde dehydrogenase 1A1 (ALDH1A1)-positive cancer stem cells in breast cancer xenografts." (PMID 24500694, 2014). "This meta-analysis indicates that ALDH1A1 is an important predictor of the progression and poor survival of breast cancer patients." (PMID 24938375, 2014). "The total number of patients was 3274, including 921 cases ALDH1A1+ breast cancer and a 2353 controls." (PMID 24938375, 2014). "Recently, it has been reported that ALDH1A1 has been related to adverse prognosis in several human malignancies, including breast cancer, lung cancer, ovarian cancer and esophageal cancer." (PMID 25253129, 2014). "The clinical relevance of this finding was investigated by using immunohistochemistry (IHC) to stain for aldehyde dehydrogenase family 1 member A1 (ALDH1A1) in 481 primary breast carcinomas." (PMID 22112299, 2011). "The group also found ALDH1A1 to be an independent prognostic factor when detected by IHC in primary breast carcinomas." (PMID 22112299, 2011). "In this study, we have focused on aldehyde dehydrogenase 1A1 (ALDH1A1), which has been recently identified to label tumour stem cells in breast cancer, colon cancer lung cancer and head and neck squamous cancer." (PMID 21708005, 2011). "Aldh1a1, which metabolizes products of lipid peroxidation, has been found to be up-regulated in human breast cancer samples." (PMID 20435547, 2010).
breast carcinoma (continued). "Recently, high aldehyde dehydrogenase 1 (ALDH1, also known as ALDH1A1) activity was shown to identify the CSC in breast cancer, lung cancer, hepatoma, head and neck, and colon cancer." (PMID 24281171, 2010). "The most compelling evidence indicating that CSCs can promote the expansion of MDSCs is the observation that ALDH1A1 activity in CSCs enhances the expansion of MDSCs through the secretion of GM-CSF, which undermines T-cell immunity and facilitates breast cancer progression." (PMID 41368628, 2025). "Notably, ALDH1A1 has been abundantly expressed in early colon cancer, and in breast cancer, it reduces the pH value in tumor cells, activating the inflammatory signal NF-κB, resulting in myeloid cell suppression and immune suppression." (PMID 39107297, 2024). "In addition, the stemness marker ALDH1A1 promotes tumor angiogenesis via retinoic acid/HIF-1α/VEGF signaling in breast cancer cells." (PMID 38953895, 2024). "Moreover, ALDH1A1, the breast cancer marker for stemness, initiates the ALDH1A1/HIF-1α/VEGF pathway through RA signaling." (PMID 39796106, 2024). "Breast cancer's stem cell number and ability to self-renew are inhibited by ALDH1A1 acetylation." (PMID 39479446, 2024). "Although not the focus of this study, we did include some analyses on ALDH1A1 that suggest it could also affect the balance of ALDH+ versus CD24−CD44+ breast cancer cells." (PMID 39251846, 2024). "Moreover, PGD2 also inhibited the expression of ALDH1A1, a breast cancer stem cell marker, which inhibited breast cancer angiogenesis and the self-renewal ability of breast cancer cells." (PMID 38704736, 2024). "Recent efforts have suggested that ALDH1A1 is regulated at the posttranslational level by the Notch signalling pathway in breast cancer, which modulates ALDH1A1 acetylation through the induction of SIRT2 expression and therefore activates ALDH1A1 to promote tumorigenesis and tumour growth." (PMID 36651035, 2023). "In the beginning, high ALDH activity enriched in CSCs is exclusively attributed to ALDH1A1, whereas in recent years this high activity has been associated with other isoforms, such as ALDH1A399 in breast cancer, ALDH1B1100 in colon cancer, ALDH3A1101 in gastric cancer (GC), and ALDH7A1102 in PCa." (PMID 36694633, 2023). "For example, silencing of the ALDH1A1 gene in human breast cancer cells increases their sensitivity to paclitaxel by triggering the production of ROS, and similar results are obtained with other anticancer agents such as doxorubicin, sorafenib, and staurosporine." (PMID 36694633, 2023). "An ALDH1A1 knockdown cell line should be constructed in future studies to investigate whether VPA treatment could result in cisplatin resistance in breast cancer cells; this might verify our present data in other aspects." (PMID 37954205, 2023). "The low expression of CD24 and high expression of aldehyde dehydrogenase 1 family member A1 (ALDH1A1) may define subsets of breast cancer stem cells with enhanced migratory potential." (PMID 37794509, 2023). "In addition, preclinical studies have confirmed that DSF in combination with gemcitabine or programmed death‐ligand 1 (PD‐L1) antibody efficiently inhibits 4T1 breast cancer tumorigenicity and growth by targeting ALDH1A1 enriched CSCs and MDSCs, respectively." (PMID 36694633, 2023). "ALDHs may play an important role in the chemo-resistance ability, clonogenicity, and spherogenesis of the cancer stem cell, and the ALDH1A1 expression was correlated with poorer overall survival in breast cancer patients." (PMID 37954205, 2023). "Extensive and in-depth studies on ALDH1A1 have been performed in breast cancer patients." (PMID 35814382, 2022). "HIF-1α can induce the expression of ALDH1A1 in breast cancer cells under hypoxic conditions." (PMID 36139678, 2022). "Aldehyde dehydrogenase 1A1 (ALDH1A1) can be used to identify breast cancer stem cells (CSC)." (PMID 36139578, 2022).